ARNT (aryl hydrocarbon receptor nuclear translocator)
Diseases named in the same sentence as ARNT in open-access papers (continued):
Sharing a sentence is not in itself a finding about the gene and the disease.
tumor (145 papers, 2007 to 2026). "A deficiency in ARNT exacerbates the formation of neutrophil extracellular traps (NETs) and the release of inflammatory cytokines, thereby deteriorating the tumor microenvironment." (PMID 40718835, 2025). "ARNT deficiency enhances the migration and functional activities of neutrophils under physiological conditions and pathological tumor microenvironment." (PMID 36859266, 2023). "The results of our study demonstrate that ARNT depletion renders tumour cells susceptible to radiation whereas overexpression of this transcription factor promotes radioresistance." (PMID 26572229, 2015). "Loss of HIF-1α and ARNT also leads to an increased response to radiotherapy, a reduction in tumor growth, and decreased angiogenesis in tumors transplanted into immune-deficient mice." (PMID 25839165, 2015). "Our previous studies have shown that ARNT cooperated with Sp1 to regulate the expression of genes that were associated with tumor growth." (PMID 25839165, 2015). "The results of this study indicate that ARNT depletion renders tumour cells susceptible to radiation whereas overexpression of this transcription factor confers radioresistance." (PMID 26572229, 2015). "Loss of HIF-1α and ARNT also leads to an increased response to radiotherapy, a reduction in tumor growth, and decrease in angiogenesis in tumors transplanted into immune-deficient mice." (PMID 24921657, 2014). "Moreover, ARNT has been linked to various aspects of malignant transformation, including tumorigenesis, tumor progression, and therapeutic resistance." (PMID 38806469, 2024). "ARNT is also linked to the risk of tumor progression, tumor invasion, and metastasis." (PMID 37508425, 2023). "Next, we sought to further clarify whether oxidative phosphorylation also contributes to ARNT depletion-associated tumor metastasis." (PMID 33446631, 2021). "Interestingly, AHR and HIF-1α share the dimerization partner ARNT/HIF1β, showing linked processes of tumor progression, metabolic pathways, and vascular development." (PMID 34572746, 2021). "In addition, ARNT deficiency in tumor cells manipulated the glycolytic pathway through enhancement of the glucose uptake rate, which reduced glucose dependence." (PMID 33446631, 2021). "In addition, we found that PDK1 downregulation, as well as ARNT knockdown caused a switch in glucose consumption to initiate tumor metastasis." (PMID 33446631, 2021). "In addition, ARNT is associated with the proliferation and survival of tumor cell lines by regulating cellular processes." (PMID 29229987, 2017). "Furthermore, the hypoxic signal mediated by the HIF-1α-ARNT transcriptional complex also causes expression of genes associated with tumour growth and metastasis." (PMID 28798482, 2017). "Inhibition of ARNT expression might therefore render appropriate tumour cells more susceptible to radiotherapy." (PMID 26572229, 2015). "The results demonstrated that ARNT expression was significantly higher in GBM compared to non-tumor tissues." (PMID 38806469, 2024). "Compared with the vehicle group, ARNT overexpression exacerbated the tumor sizes in mice (P < 0.01)." (PMID 38831978, 2024). "Despite these findings implicating ARNT in tumor development and aggression, the specific molecular mechanisms underlying the ARNT-GBM relationship remain to be elucidated." (PMID 38806469, 2024). "Although ARNT plays an important role in regulating the function and recruitment of tumor-infiltrating neutrophils, it is obvious that these effects depend on alterations in gut microbiota homeostasis in the tumorigenic microenvironment." (PMID 36859266, 2023). "Herein, our data demonstrated that ARNT negatively regulated the recruitment and function of neutrophils under physiological conditions or in the tumor microenvironment." (PMID 36859266, 2023). "One study overexpressed ARNT in Hepa-1 cells in vitro, and according to the kinetic data, ARNT probably plays an important role in the early stage of tumor growth." (PMID 36859266, 2023).
tumor (continued). "ARNT is a protein shown to be involved in regulating tumor growth and angiogenesis along with its binding partner aryl hydrocarbon receptor (AHR)." (PMID 35197309, 2022). "The aryl hydrocarbon receptor nuclear translocator (ARNT) gene, also named HIF‐1β, locates in 1q21, which play a critical role in driving tumor growth and metastasis." (PMID 35192745, 2022). "In the Hif1α signaling pathway, TME-derived growth factors IGF and EGF are likely promoting HCC-tumor derived ARNT, which is in turn promoting the expression of known pro-angiogenesis genes PAI1, and TGFA." (PMID 33995488, 2021). "Additional deletion of HIF-2α or its binding partner aryl hydrocarbon receptor nuclear translocator (ARNT) enhanced tumor development." (PMID 34294128, 2021). "On the contrary, our previous studies show that decreased expression of ARNT by miR-107 targeting enhances tumor metastasis." (PMID 33446631, 2021). "Intriguingly, CCCP and NAC dramatically inhibited ARNT and PDK1 deficiency-induced tumor cell extravasation in mouse models." (PMID 33446631, 2021). "This is evidenced by increased expression of HCC tumor-derived genes downstream of the Hif1α-ARNT complex." (PMID 33995488, 2021). "We found that ARNT and PDK1 deficiency prevented apoptosis in tumor cells that were deprived of glucose, which indicates that the glycolytic switch from aerobic glycolysis to oxidative phosphorylation is essential for cell survival during metastasis." (PMID 33446631, 2021). "Although the molecular mechanisms involved in bHLH-PAS family-regulated tumor progression and metastasis have become better understood in recent years, the precise role of ARNT in tumorigenesis is still unclear." (PMID 33446631, 2021). "HIF3A expression was evenly distributed in the different tumor zones, while HIF1A, HIF2A, and ARNT expressions were enriched in the perinecrotic zones and/or in blood vessels of the tumor (Online Resource 9)." (PMID 29149419, 2018). "Recently it was shown by our group that ARNT overexpression confers a radioresistant phenotype in tumour cells (including Hep3B)." (PMID 28855849, 2017). "CUR inhibits HIF-1 in certain HCC cell lines and in vivo studies with tumor xenografts This was shown to occur by CUR inducing the degradation of the aryl hydrocarbon receptor nuclear translocator (ARNT)." (PMID 28611316, 2017). "ARNT overexpression in tumour cells conferred radioresistance whereas knockdown of ARNT had the opposite effect." (PMID 28855849, 2017). "We previously found that ARNT expression was decreased in tumor cells that were treated with cisplatin." (PMID 25839165, 2015). "ARNT expression is required for tumor cell growth in most cancers; therefore, ARNT is considered a target for cancer therapy." (PMID 25839165, 2015). "We also found that miR-107 overexpression significantly inhibited ARNT expression and promoted tumor cell invasion." (PMID 25839165, 2015). "The aim of this study was to elucidate the effects of ARNT silencing and overexpression in different tumour cell lines regarding radioresistance." (PMID 26572229, 2015). "In conclusion, we provide strong evidence that ARNT depletion enhances tumor migration and invasion through activation of the fibronectin/integrin β1/FAK signaling axis." (PMID 25839165, 2015). "According to the majority of literature, ARNT is regarded to be constitutively expressed but certain tumour cell lines are capable to elevate ARNT in hypoxia." (PMID 26572229, 2015). "The aryl hydrocarbon receptor nuclear translocator (ARNT) is broadly involved in regulating tumorigenesis by inducing genes that are involved in tumor growth and angiogenesis." (PMID 25839165, 2015). "ARNT is generally considered as constitutively expressed but emerging evidence indicates the capability of certain tumour cells to upregulate ARNT in response to hypoxia." (PMID 26572229, 2015). "The aryl hydrocarbon receptor nuclear translocator (ARNT) is an important mediator of tumor progression." (PMID 24921657, 2014).
tumor (continued). "ARNT also plays vital role in regulating tumor progression, detoxification, and efflux of anti-cancer drugs, which increases the survival chance in adverse circumstances." (PMID 24921657, 2014). "The elevated activity of ATF6 and aryl hydrocarbon receptor nuclear translocator (ARNT) in γδ T cells may synergistically assist these cells in adapting to the hypoxic and metabolic stresses present in the tumor microenvironment." (PMID 41155287, 2025). "ARNT expression was elevated in tumor samples compared to adjacent non-tumor tissues." (PMID 38806469, 2024). "Moreover, the expression of ARNT-mRNA in tumor-infiltrating neutrophils was higher than in mature neutrophils under physiological conditions." (PMID 36859266, 2023). "Additionally, these data also suggest that ARNT is important for all neutrophil populations with regulatory activities under physiological or tumor conditions." (PMID 36859266, 2023). "However, the new data reveal that in ccRCC tumours, competition for HIF-1β/ARNT results in a reciprocal relationship between HIF and AHR and constitutive activation of HIF is associated with suppression of the AHR pathway." (PMID 36725335, 2023). "For example, the HIF1α/ARNT complex promotes tumor angiogenesis, erythropoiesis and glycolysis." (PMID 33446631, 2021). "We previously reported that ARNT depletion triggers tumor cell metastasis." (PMID 33446631, 2021). "Interestingly, AHR had been shown to cooperate with HIF1α through the commonly shared partner, AHR nuclear translocator (ARNT/HIF1β), to orchestrate glycolysis and tumor microenvironment." (PMID 32226544, 2020). "It was demonstrated that high ARNT protein levels mediate radioresistance in tumour cells." (PMID 28855849, 2017). "ARNT may play a positive role in tumor growth (in either early-stage tumor growth or in metastatic organs) but plays a negative role in tumor migration and invasion." (PMID 25839165, 2015). "ARNT expression in the tumor tissues was lower in deep sites compared to superficial sites." (PMID 25839165, 2015). "Interestingly, the promoter activity of aurora C, which confers tumor growth during tumorigenesis, was further increased in cells that co-expressed ARNT and AhR." (PMID 25839165, 2015). "Coinciding with our finding that ARNT expression plays a dual role in both the enhancement of tumor growth and the inhibition of migration and invasion, several reports have also noted the opposing features of tumor growth and metastasis that are regulated by oncoproteins." (PMID 25839165, 2015). "Interestingly, chemotherapeutic drugs inhibited ARNT expression and promoted the invasion of residual tumor cells." (PMID 25839165, 2015). "Additionally, neutrophils deficient in ARNT have been shown to augment NET formation and inflammatory responses through CXCR2 signaling, which subsequently activates the NF-κB pathway and promotes tumor growth." (PMID 40718835, 2025). "Therefore, ARNT mutations may play a role in HIF-1 complex activation and promote tumor angiogenesis, which may appear as an increase in the mean transit time on CEUS." (PMID 37120792, 2023). "However, recent studies suggest that ARNT may also play an important role, especially in tumor growth." (PMID 36859266, 2023). "Therefore, our results suggest that the hypoxic microenvironment in ACP might influence the activation of ARNT and the promotion of tumor cell migration." (PMID 34707096, 2021). "Indeed, knockdown of ARNT protected cells from glucose and L-glutamine deprivation-induced cell apoptosis, which indicates that ARNT depletion reduces the glucose dependence of these tumor cells." (PMID 33446631, 2021). "In addition, ARNT may play a role in tumor angiogenesis via its capacity to bind xenobiotic responsive elements to induce transcription." (PMID 34179020, 2021). "Therefore, we studied whether the expression of ARNT was controlled by miR-107, resulting in enhancement of tumor cell metastasis." (PMID 25839165, 2015).
tumor (continued). "On the basis of these findings, it appears that the inactivation of ARNT or its partners, such as Sp1 and AhR, inhibits tumor growth; however, it may also promote metastasis, allowing tumor cells to escape from their immediate environment, such as during targeted therapy." (PMID 25839165, 2015). "HIF-2α inhibitors such as PT2385 and belzutifan aim to halt these adaptive responses by preventing HIF-α dimerization with ARNT, while VEGF inhibitors correct tumor oxygenation by suppressing abnormal vascularization." (PMID 41575610, 2026). "The downregulation of ARNT and PDK1, accompanied by ROS production, indicates a high incidence of tumor metastasis." (PMID 33446631, 2021). "Our results with ARNT knockout KP mice caution against the use of pan-HIFα inhibitors for the treatment of STS and potentially for other tumours as well." (PMID 26837714, 2016). "ARNT depletion promoted the activation of the fibronectin/integrin β1/FAK signaling axis and increased tumor invasion and migration." (PMID 25839165, 2015). "However, the role of ARNT in tumor metastasis during normoxia remains unclear." (PMID 25839165, 2015). "Depletion of ARNT by siRNA conferred Hep3B and MCF-7 tumour cells a radiosensitive phenotype whereas overexpression promotes radioresistance." (PMID 26572229, 2015). "Although this observation is consistent with a selective growth advantage conferred to cells by ARNT and GDI2, larger sets of primary-metastatic tumor pairs will be needed to verify this trend." (PMID 25059231, 2014). "The C3TFT gene-sets that were more highlyexpressed in the tumour tissue had common regulatory motives for various E2Fs, NRF2, ARNT, NRF1, MYC and YY1." (PMID 23009663, 2012). "Hypoxia-Inducible Factor (HIF), a protein complex composed of either HIF1a or HIF2a and HIF1b/ARNT subunits, activates genes involved in angiogenesis and cell proliferation, and is central to the tumor’s adaptation to low oxygen, contributing to a neoplastic phenotype." (PMID 40500522, 2025). "Stage IIA, when the tumor has grown large but not yet metastasized to the lymph largely contains cluster 5 fibroblasts, which have high HIF1A, as well as ARNT that encodes HIF-1β subunit of the HIF complex." (PMID 35565326, 2022). "The ARNT/Sp1/c-Jun complex also regulates MDR1 expression and EGF-induced gene expression, such as that of cyclooxygenase-2, p21WAF1/CIP1 and 12(S)-lipoxygenase, which contribute to cancer drug resistance and tumor metastasis." (PMID 33446631, 2021). "The results demonstrated that downregulation of the ARNT/PDK1 axis and the increase in ROS may confer tumor cells with the ability to metastasis." (PMID 33446631, 2021). "AhR and its nuclear translocator ARNT are expressed in most if not all cells and tissues of the body, including immune and tumor cells." (PMID 31481962, 2019). "Although tumorigenesis usually involves normoxic conditions, the functional role of ARNT in the regulation of tumor metastasis is not well characterized under normoxic conditions." (PMID 25839165, 2015). "The transcription factor Aryl hydrocarbon receptor nuclear translocator (ARNT), also designated as Hypoxia-inducible factor (HIF)-1β, is part of the HIF pathway which mediates cellular adaptations to oxygen deprivation and facilitates tumour progression." (PMID 26572229, 2015). "The hypoxia response, which plays a role in tumor development, presumably prioritizes the function of HIF-1β rather than that of ARNT." (PMID 25068796, 2014). "Furthermore, HIF-1α could be transferred to the nucleus to bind to ARNT, which enhanced HIF signaling and may be beneficial to tumor cells." (PMID 38831978, 2024). "Importantly, CD11b+Gr1+ neutrophils depletion significantly reversed the tumor-promoting effects of Arnt−/− mice, suggesting that the absence of ARNT in neutrophils plays a key role in tumorigenesis." (PMID 36859266, 2023).
tumor (continued). "The deregulation of HIF2α could promote tumor development, but HIF2α had an undeveloped function that was largely independent of ARNT, which could affect gene transcription, cell differentiation, proliferation, and tumor metastasis and growth." (PMID 33828526, 2021). "ARNT expression in individual tumor specimens was characterized as absent, low or high." (PMID 25839165, 2015). "Our findings show for the first time that ARNT may play both a positive role in tumor growth in either early-stage cancer or in metastatic organs and a negative role in tumor invasion and migration." (PMID 25839165, 2015). "In addition, decreased ARNT expression was observed in lymph-vascular invasion samples compared to neighboring non-metastatic tumor tissue (red arrow)." (PMID 25839165, 2015). "The transcription factor Aryl hydrocarbon receptor nuclear translocator (ARNT), also known as Hypoxia-inducible factor (HIF)-1β, is part of the HIF signalling pathway which mediates cellular adaptations to oxygen deprivation and contributes to radioresistance of neoplasms." (PMID 26572229, 2015). "Moreover, the AhR pathway, which involves HIF-1β (ARNT), is known to mediate anti-tumor effects." (PMID 25068796, 2014). "Furthermore, recent studies have identified multiple additional pathways through which ARNT may contribute to tumor initiation, progression, and drug resistance, including the fibronectin/integrin β1/FAK, Myc/Miz/CDKN2B, NF-κB, p38α-MAPK, and canonical AHR/ARNT signaling pathways." (PMID 39684472, 2024). "When the cultured tumor cells were treated with 1 μM B[a]P, there were no changes in mRNA expression of HIF-1α, its target genes, ARNT, AhR, and its target gene CYP1B1." (PMID 37305351, 2023). "mRNA levels of HIF-1α, AhR, and of their target genes as well as of ARNT and nuclear receptor coactivator NCOA2 were determined in tumor tissues from patients in whom the tumor was promptly removed either with or without prior endovascular embolization." (PMID 37305351, 2023). "Although the absence of ARNT significantly promotes the expression of CXCR2 in neutrophils of BMs and spleen under physiological conditions and pathological tumor-infiltrating neutrophils, can CXCR2 mediate the regulation of ARNT deficiency on neutrophil function?" (PMID 36859266, 2023).